MXI1 (MAX interactor 1, dimerization protein)
Diseases named in the same sentence as MXI1 in open-access papers (continued):
Sharing a sentence is not in itself a finding about the gene and the disease.
pulmonary fibrosis (1 paper, 2022). Chronic progressive interstitial lung disorder characterized by the replacement of the lung tissue by connective tissue, leading to progressive dyspnea, respiratory failure, or right heart failure. "TSC22D1 (TSC22 domain family, member 1) and MXI1 (MAX interactor 1) are also associated with pulmonary fibrosis in some transcriptomic, miRNomic, and methylation array data." (PMID 35980387, 2022).
pulmonary hypertension (1 paper, 2022). Increased pressure within the pulmonary circulation due to lung or heart disorder. "Although Mxi1 has been extensively studied in the context of carcinogenesis and well documented as a tumor suppressor, this is probably the first study to determine that it is also an important player in HPH, reminiscent of multiple shared pathomechanisms between pulmonary hypertension and cancer." (PMID 35401684, 2022).
tumor (50 papers, 1997 to 2025). "(iv) MXI1, a putative tumor suppressor encoding a MYC-antagonist, was strongly upregulated by DSK638 (bars 8 vs. 7)." (PMID 35149728, 2022). "Of the five allelic loci examined, only LOH of D10S173 at the ADD3/MXI1 locus was a predictor of shorter survival and had a significant association with tumor grade and proliferative index." (PMID 34970477, 2021). "Moreover, loss of the MNT related gene MXD1 (formerly MXI1) was found in 8/20 SS tumor specimens, suggesting that loss of MYC antagonism is a common contributing mechanism in SS tumorigenesis." (PMID 28230739, 2017). "We concluded by comparing MAX dimerization protein 3 (MXD3) and MAX interactor 1 (MXI1) expression in tumor tissues using Uniform Manifold Approximation and Projection and violin plots in the Tumor lmmune Single-cell Hub database." (PMID 39287260, 2024). "To further examine the roles of MXD3 and MXI1 in tumors, we proved that the expression of MXD3 in tumor tissue was higher than that in adjacent tissues, while the expression of MXI1 in tumor tissue was lower than that in adjacent tissues." (PMID 39287260, 2024). "Amongst these, Mxi1 has been considered a potential tumor suppressor with an inhibitory effect on the transcriptional activity of Myc." (PMID 35501353, 2022). "MAX interactor 1 (MXI1) is considered a tumor suppressor gene located in the cancer hotspot region 10q24-q25 of the human chromosome." (PMID 35602303, 2022). "It has been reported that Mxi1 suppressed the transcriptional activity of MYC to repress tumor development." (PMID 35501353, 2022). "We found that allelic loss in both D10S173 (ADD3/MXI1 locus) and D10S1137 (MGMT locus) were positively associated with tumor grading and proliferative index (MIB-1)." (PMID 34970477, 2021). "MXD (protein family transcriptional repressors like MXD1, MXI1, MXD3, and MXD4 are associated with terminal differentiation, inhibition of cell-cycle progression, and tumor suppression." (PMID 28245597, 2017). "MXI1 is considered to be a tumor suppressor gene because it acts as an antagonist of the oncogene c-Myc and negatively regulates the promoter of c-Myc." (PMID 24376632, 2013). "Paradoxically, increased expression of putative c-MYC antagonists MAD1 and MXI1 was observed in tumour specimens." (PMID 18493233, 2008). "The top list also included two cMyc regulating genes: Mxi1, a Max-binding tumor supressor that antagonizes cMyc among other things and Ztbt17 (aka Miz-1) which we have previously shown to regulate the neural crest stem cell pool via binding to c-Myc via a non-canonical pathway." (PMID 41446274, 2025). "Additionally, it has been reported that the protein encoded by MXI1 is a transcriptional repressor thought to negatively regulate MYC function 62, and is therefore a potential tumor suppressor." (PMID 37441593, 2023). "The tumor suppressor MXI1 was supposed to inhibit MYC levels by binding to the promoter of MYC; however, a large amount of miR-155 and miR-23a binds to the 3′UTR of MXI1, causing a decrease in its expression." (PMID 38125749, 2023). "To determine whether miR-300/KLF9 axis was involved in Mxi1-suppressed tumor growth, we modulated the expression of Mxi1, miR-300, and KLF9 separately or in combination." (PMID 35501353, 2022). "In addition, UBE2O has been reported to accelerate tumor progression by modulating c-myc via the UBE2O/Mxi1 axis and UBE2O/AMPKα2/mTORC1 axis." (PMID 36068586, 2022). "Therefore, it is reasonable to postulate that the role of Mxi1 in tumor progression depends, at least in part, in its regulatory effect on gene transcription." (PMID 35501353, 2022). "It is suggested that downregulation of MXI1 may contribute to tumorigenesis and correlate with the prognosis of tumor patients." (PMID 35602303, 2022).
tumor (continued). "Those proteins included HIF1α, HIF2α and their target genes c-Myc and β-catenin, as well as MXI1 and MCL-1 that are closely associated with c-Myc, EMT markers and effectors of the Akt signaling pathway that are potentially associated with tumor response to sorafenib treatment." (PMID 32545251, 2020). "These genes likely function as downstream effectors of STAT3 in GBM to regulate not only cell proliferation (e.g., GAS7, IGFBP2, MEOX2 and MXI1), and but also tumor-stroma interactions by modulating protein secretion (e.g., ANXA1, ARL4C, EMILIN1, EMP2, EXTL3 and PDIA4)." (PMID 29774125, 2018). "This suggests a potential regulatory relationship between MAX, MXI1, and DNA methylation that may extend to downstream cancer tumor development." (PMID 25616342, 2015). "Knockout experiments in mice have confirmed the tumor suppressor role of MXI1." (PMID 24376632, 2013). "Interestingly, this was accompanied by an overexpression of c-MYC antagonists MAD1 and MXI1 in many tumours." (PMID 18493233, 2008). "The overexpression of MXI1 in tumours may also, in part, be explained by the presence of differentially transcribed isoforms of MXI1 that lack important functional domains." (PMID 18493233, 2008). "This gene does not appear to be MXI-1, which has been implicated in some other human tumour types." (PMID 11401316, 2001). "The other four (EPAS1, MXI1, ARNT2, and E2F1) relate to the signaling pathways involved in the processes of tumor formation and development." (PMID 40724805, 2025). "Our results suggested that FOSL1, CEBPD, MXI1 and YY1 were critical TFs of tumor invasion induced by hypoxia, and they can be used as an independent prognostic signature to predict GBM survival." (PMID 37441593, 2023). "The abnormal expression of miR-105 in EV is the result of the MYC oncoprotein in BC cells and in turn, acts on MXI1 in CAFs and activates MYC signaling to induce a metabolic program that is suitable for tumor growth." (PMID 31281797, 2019). "MYC functions can be antagonized by the interaction between MXD/MXI1 bHLHZip transcription factor proteins, which in turn suppress MYC mediated transformation and tumor growth." (PMID 28245597, 2017). "It is also clear that a number of the candidate drivers including MXI1, SIN3A, THAP1 and ATF3 are down-regulated in PRAD tumours." (PMID 28592290, 2017). "As previous studies have shown that MXI1 and PTEN were both involved in GBM as tumor suppressor genes for their abilities to regulate tumor cell growth, migration, and apoptosis, we decided to focus on NLK." (PMID 26023737, 2015). "For example, DKK1, HTATIP2, HBP1, MXI1 and CASP7, all bound by RBM47 and upregulated upon RBM47 reintroduction, have known tumor suppressive functions." (PMID 24898756, 2014). "The increased activity of MXI1 could attenuate MYC-mediated transcription, thereby mitigating MYC-driven metabolic regulation and limiting abnormal tumor cell proliferation." (PMID 40672941, 2025). "HIF-1α decreases the level of MYC by inducing the transcription of MAX interactor 1 (MXI1) (a repressor of MYC) in cancer cells and enhances mitochondrial respiration but increases the glycolysis, leading to tumor growth and survival in a low oxygen environment." (PMID 35798726, 2022). "These properties of mdl-1 mutants recapitulate effects of Mad TFs in mammals, e.g. mice lacking the Mad TF Mxi1 show hyperplasia in a number of tissues (e.g. prostatic epithelium), and are tumor prone." (PMID 24531613, 2014). "Some genetic testing methods may be feasible for determining whether tumor tissues highly express RUNX1 and the corresponding downstream genes (BCL3, MGP, and MXI1), consistent with our experimentally validated results: in positive cases, targeting RUNX1 may be a suitable optional treatment." (PMID 31754093, 2019). "Moreover, MXI1 and other members of the MXD family may fall in this same class of tumor suppressors." (PMID 28230739, 2017).
cancer (27 papers, 1997 to 2025). A tumor composed of atypical neoplastic, often pleomorphic cells that invade other tissues. "For individual genes, high expression was also more commonly associated with unfavorable prognosis, although many genes also had favorable associations in certain cancer types (e.g. MXI1)." (PMID 33654095, 2021). "In addition, GSCA also recovered associations with MAX and the MAX interacting protein MXI1, both of which have also been linked to a range of human cancers." (PMID 23220237, 2013). "Although the relevance of MXI1 to cancer metastasis remains unexplored, our data, together with the previous observations that MYC and E2F1 promote epithelial-mesenchymal transition and metastasis, implicate MXI1 in metastasis-suppression." (PMID 35149728, 2022). "Depletion of UBE2O with specific siRNAs led to an elevation in endogenous Mxi1 protein levels in different cancer cells under steady-state conditions and after DNA damage." (PMID 32901121, 2021). "MYC-associated protein X interactor-1 (MXI1) is an antagonist of the oncogenic MYC protein, and the deletion of the MXI1 gene causes many kinds of human cancers." (PMID 33489894, 2020). "MAX interactor 1 (Mxi1) is located in the cancer hotspot region 10q24-q25 of human chromosomes." (PMID 32901121, 2021). "The function of the proteins overexpressed in cancer, such as CAIX, PDK, BNip3, Mxi-1, VEGF, and EPO, is regulated by HIF-1a in acute hypoxia." (PMID 36294785, 2022). "HIF-1-induces MAX-interacting protein 1 (MXI-1), which competes with MAX for binding with c-MYC to repress c-MYC activity, in hypoxic cancer cells." (PMID 34359884, 2021). "MXI1 is a transcriptional repressor that negatively regulates the function of MYC, the accumulation of which activates cell cycle progression and cellular transformation in several cancers." (PMID 39599858, 2024). "Compared with MXI1, less is known about the role of ADD3 in cancer." (PMID 34970477, 2021). "In addition to these five TFs, we identified BATF, SMARCB1, TAF1 and MXI1 as novel TERT regulators across cancer entities that to our knowledge, so far, have not been described in the literature as TERT regulators." (PMID 31888467, 2019). "For modules M3, M4, and M5, although the corresponding GO_BP terms were not directly related to cancer, we found PrCa-relevant genes in these three modules, including BTG2, FOS (also known as c-Fos), and CXCR4 in module M3; ARFGAP3 and CDH1 in module M4; and SMAD3 and MXI1 in module M5." (PMID 25418933, 2014).
infection (4 papers, 2016 to 2024). The state of being infected such as from the introduction of a foreign agent such as serum, vaccine, antigenic substance or organism. "The level of lnc-SMNDC1-1 increased more than 8-fold upon infection, and we were able to correlate this lncRNA with the protein-coding gene MXI1." (PMID 27958323, 2016). "Additionally, we identified 10 genomic regions associated with breakthrough infection (SLC6A20, ST6GAL1, MUC16, FUT6, MXI1, MUC4, HMGN2P18-KRTCAP2, NFKBIZ and APOC1), and one with breakthrough severity (APOE)." (PMID 39384777, 2024). "Interestingly, in this present study, whereas PCPEC displayed a strong inflammatory response to infection, genes attributed to hypoxia were found to play a more prominent role during infection in HIBCPP cells (including ZFP36L1, MXI1, KLHL24, PNRC1, CDKN1C, and DUSP2)." (PMID 33763387, 2021).
MXI1 also shares sentences with these, for which no sentence is quoted: Bacterial Infections (2 papers); NUT carcinoma (2); renal cell carcinoma (2); squamous cell carcinoma (2); acute leukemia (1); adenocarcinoma (1); brain cancer (1); diabetes (1); discoid lupus erythematosus (1); leukemia (1); metastatic tumors (1); myeloid leukemia (1); myeloma (1); nasopharyngeal carcinoma (1); prostate adenocarcinoma (1); rectal cancer (1); sarcoma (1); squamous cell carcinoma of the skin (1).